POSTN (periostin)
Diseases named in the same sentence as POSTN in open-access papers (continued):
Sharing a sentence is not in itself a finding about the gene and the disease.
tumor (continued). "The impact of tumor burden on sRANKL, periostin, and osteopontin serum levels was evaluated by dividing the patients into two groups according to the BMI by MPCs using a cut-off of 60%." (PMID 38067265, 2023). "POSTN has already been studied in humans in several normal tissues, inflammatory processes, and neoplasms, revealing an important role in tumor progression in various types of cancer, such as colon, lung, head and neck, breast, ovarian, and prostate." (PMID 38076555, 2023). "According to one study, the overexpression of periostin can also be observed in HNSCC, which is associated with tumor proliferation and metastasis." (PMID 38003931, 2023). "POSTN regulates multiple biological behaviors of tumor cells, including proliferation, survival, invasion, angiogenesis, metastasis, and chemoresistance." (PMID 38076555, 2023). "POSTN+ myCAFs were significantly enriched in advanced tumours and presented gene signatures related to pro‐invasion and ECM remodeling." (PMID 38115703, 2023). "As with many oncogenes targeted by the let-7 family, periostin expression correlates directly with tumor grade and indirectly with survival in glioma." (PMID 37370851, 2023). "Periostin is a secreted ECM protein encoded by the POSTN gene, which, among other things, enhances tumor metastatic activity and stimulates the formation of tumor stem cells in HNSCC." (PMID 38003931, 2023). "Many of the metastatic phenotypes of our preclinical models were observed in clinical tumor specimens, including VHL loss resulting in the upregulation of HIF-1α and POSTN." (PMID 37069149, 2023). "The expression of POSTN (R=0.521) and FAP (R=0.606) was correlated with that of CD163 (p<0.001), which is a characteristic gene of tumour-associated macrophages (TAMs)." (PMID 37199594, 2023). "In GC tumour tissue sections, there were fibroblast-like cells with double-positive for POSTN and FAP staining according to IF." (PMID 37199594, 2023). "To determine if DDR2′s regulation of periostin in CAFs influences tumor metastasis in cell-based assays, we performed attachment, clearance, and invasion assays." (PMID 35884543, 2022). "We evaluated the correlation between the expression of POSTN and 28 tumour immune infiltrating cell subtypes." (PMID 35508298, 2022). "Many studies indicate that POSTN plays an important role in tumor growth and the formation of new blood and lymphatic vessels in its proximity." (PMID 36077762, 2022). "Tumor-derived eCAFs (Cluster 3) are characterized by high expression of genes associated with tumor invasion (MMP14, LOXL2, and POSTN), indicating that eCAFs constitute an essential component of the TME for tumor metastasis." (PMID 34976204, 2022). "The correlation analysis showed a strong positive significant (r = 0.7085, **** p < 0.0001) correlation of POSTN expression in the cytoplasm of cancer cells with POSTN expression in tumor stromal cells (CAFs) in the whole cohort." (PMID 35163164, 2022). "Overexpression of POSTN in DDR2-depleted CAFs led to an increased ability to promote tumor cell migration and proliferation." (PMID 35884543, 2022). "DDR2 and periostin signaling in CAFs promotes tumor migration, clearance, proliferation, and invasion." (PMID 35884543, 2022). "Periostin (POSTN), playing a crucial role in some biological processes, is considered to be associated with tumor progression." (PMID 35559040, 2022). "Periostin expression upregulated in triple negative breast cancer xenograft following chemotherapy in tumor cells and promoted invasion of residual of tumour cells." (PMID 36224629, 2022). "This leads to cytokine/chemokine production from cancer cells to facilitate monocyte infiltration and differentiation to enrich M2 macrophages in the tumor microenvironment, at the same time, POSTN also mediates TGF-β2 expression to promote CAF activation." (PMID 36550569, 2022).
tumor (continued). "With regard to the prognostic power, the current study demonstrated that the status of stromal periostin expression stratified patients by survival outcome more effectively than the status of tumor budding, consistent with a previous study." (PMID 35850759, 2022). "Previous research once found a wide variability of POSTN expression in a different histological subtype of PTC, and high stromal POSTN expression is associated with aggressive tumor behavior." (PMID 36120433, 2022). "It was reported that periostin protein derived from tumor fibroblasts determined the lung metastasis efficiency of breast cancer and the size of metastatic cancer." (PMID 35719975, 2022). "The metastatic potential of tumor cells is also influenced by matricellular proteins like periostin (POSTN)." (PMID 35884543, 2022). "In our study, the levels of periostin in the tissue margin correlated positively with the margin and tumor levels of TNFα Additionally, we observed correlation between periostin and TNFα in tumor tissue." (PMID 35056404, 2022). "Periostin expression has been reported to correlate with vascular endothelial growth factor-C (VEGF-C) expression in both the tumor and serum of HNC patients." (PMID 36224629, 2022). "Currently, many studies have indicated that the overexpression of POSTN is connected with tumor progression." (PMID 35163164, 2022). "For the Matrigel transwell invasion assay, we used conditioned media from DDR2-expressing, DDR2-depleted, and DDR2-depleted + POSTN-overexpressing CAFs as chemoattractant for tumor cell invasion." (PMID 35884543, 2022). "For comparison, POSTN expression was more strongly correlated with the macrophage fraction in TCGA tumor samples, which is the most highly correlated gene even after correction for the overall stromal fraction in tumor samples." (PMID 34976204, 2022). "We aimed to identify if DDR2 expression in tumor cells regulates POSTN expression, so we performed immunoblotting on a panel of DDR2-expressing and DDR2-depleted cells." (PMID 35884543, 2022). "Suppression of periostin inhibited the growth and invasion of mesenchymal tumor cells.The presented data show the role of periostin in cancer cell proliferation, survival and tumor growth." (PMID 36224629, 2022). "Ectopic expression of POSTN enhanced whereas knockdown of POSTN decreased cancer cell migration and invasion in vitro, as well as tumor growth and metastasis in vivo." (PMID 36550569, 2022). "In their study, they showed that higher levels of POSTN in cancer epithelial cells correlated with higher tumor stage, lymph node metastases, and poor overall survival." (PMID 35163164, 2022). "This difference can be explained by the fact that POSTN does not only affect tumor cells but it also influences the cells surrounding the tumor, such as endothelial cells." (PMID 36077762, 2022). "The second crucial role of periostin in tumor development is the promotion of angiogenesis through the up-regulation of vascular endothelial growth factor receptor 2 expression." (PMID 35056404, 2022). "In metastatic lungs, CAFs have been reported to produce POSTN in response to TGF-β released by infiltrating tumor cells." (PMID 35567669, 2022). "In order to determine the role of DDR2′s modulation of POSTN on tumor cell spreading and proliferation, we performed spheroid spreading and wound healing assays." (PMID 35884543, 2022). "In a murine model of TSCC, the authors found that BMSCs promoted tumor growth, invasion, metastasis and enhanced the expression of periostin in tumor tissues." (PMID 35846142, 2022). "According to a previous study, POSTN is expressed by fibroblasts in normal tissue and the stroma of the primary tumour and plays a role in cancer stem cell maintenance and metastasis." (PMID 35865633, 2022). "We found that the POSTN pathway (POSTN-ITGAV/ITGB5) was enhanced from GCTB tumor cells to TAMs after DMAB treatment." (PMID 36172351, 2022).
tumor (continued). "In conclusion, periostin activates the proliferation and migration of tumor cells by the ILK/AKT/mTOR pathway." (PMID 35676936, 2022). "We aimed to define the role of DDR2′s modulation of POSTN in CAFs on tumor cell invasion into the basement membrane and ECM migration." (PMID 35884543, 2022). "POSTN functions in the migration and adhesion of normal cells, but also affects tumor cell proliferation, apoptosis, and invasion, and angiogenesis." (PMID 35057799, 2022). "The experimental demonstration that LN metastasis can feed the dissemination to distant organs demonstrated that LN PM niche and LN metastasis are worth treating although POSTN has been reported to promote tumor cell proliferation, migration and invasion." (PMID 35567669, 2022). "In summary, the results of this study demonstrate the important functional and molecular mechanisms of POSTN in tumor invasion." (PMID 35163164, 2022). "We assessed the relationship between the expression level of POSTN and MMP-2 in NSCLC and found a positive significant correlation of POSTN expression level with MMP-2 in tumor cells (r = 0.5262, *** p < 0.001)." (PMID 35163164, 2022). "Tumor-derived POSTN is important for the recruitment of M2-like macrophages during tumor progression." (PMID 35884543, 2022). "eCAFs were also shown to promote metastasis and even tumor growth through interacting with M2 macrophages via periostin (protein of POSTN)." (PMID 35757757, 2022). "The ability of POSTN to support the adhesion and proliferation of LEC and tumor cells was investigated by using recombinant POSTN." (PMID 35567669, 2022). "Three days post-injection, a significant reduction of tumor area was detected in LNs of mice injected with tumor cells and anti-POSTN antibody." (PMID 35567669, 2022). "This is partly due to migration of peripheral macrophages to tumours driven by secreted factors such as periostin (POSTN)." (PMID 36230865, 2022). "By contrast, GB-induced CMA in PCs induces a secretome with high levels of proteins that can promote tumor angiogenesis and facilitate pro-tumor immune responses (e.g., angiotensin, gelsolin, periostin, and osteopontin)." (PMID 36012149, 2022). "Their study revealed that tumor cells (A549) with silenced POSTN expression had significantly reduced expression levels of Snail protein, which was responsible for EMT induction." (PMID 36077762, 2022). "The periostin-positive area was increased in the order of tumor gland, invasive front, and distal stroma, indicating that eCAFs mainly reside in the distal stroma area." (PMID 34976204, 2022). "The hub genes in nontumour tissues are GADD45A and IL-36G, while the hub genes in tumour tissues are POSTN and APOH." (PMID 36065314, 2022). "Little is known about the role of periostin in establishing a dysfunctional tumor-supportive microenvironment." (PMID 35887333, 2022). "It shares almost 50% similarity with periostin and has been assigned roles as both a tumor suppressor and a tumor promoter in different experimental systems." (PMID 36077607, 2022). "A positive correlation was demonstrated between POSTN expression and tumor microvessel density in LUAD." (PMID 35832544, 2022). "This analysis identified fibronectin and periostin to be elevated in the hearts of PE-infused tumor-bearing mice." (PMID 35406672, 2022). "Periostin was a multifunctional extracellular matrix protein, which was expressed by fibroblasts in the normal tissue and in the stroma of the primary tumor." (PMID 35719975, 2022). "Postn, which encodes Periostin, was the most significantly altered DEG in our transcriptomic profiling and the gene most significantly associated with the immunosuppressed tumor microenvironment in HCC." (PMID 35676936, 2022). "We first identified that tumor cells co-cultured with DDR2-expressing fibroblasts had lower periostin expression when compared to tumor cells co-cultured with DDR2-depleted fibroblasts." (PMID 35884543, 2022).
tumor (continued). "For instance, human ccRCC tumor cell lines are known to induce periostin accumulation and to activate NIH3T3 mouse fibroblasts, and these activated fibroblasts then enhance ccRCC cell attachment in vitro." (PMID 35886951, 2022). "The function of this molecule in tumor progression along with its expression in cancerous tissues and its low expression in normal tissues makes periostin an attractive therapeutic target." (PMID 36224629, 2022). "Genetic deletion of POSTN in RIP1-Tag2 mice blunted tumor rebounds of M2-like macrophages and αSMA+ stromal cells in response to prolonged VEGFA inhibition." (PMID 36077762, 2022). "This seems to be in line with our further findings of positive correlations between periostin tumor concentration and tumor budding." (PMID 35056404, 2022). "We also assessed effects of PDE5i treatment on CAF differentiation in vivo by conducting immunohistochemistry (IHC) for the CAF markers α-SMA and periostin in PDX tumor sections." (PMID 35732148, 2022). "Overexpression of POSTN in DDR2-depleted CAFs (CAF shDDR2 POSTN OE + ES2) led to increased tumor burden in our xenograft model." (PMID 35884543, 2022). "Periostin exerts an integral role in the crosstalk between tumor cells and tumor microenvironments, cell and matrix, physiological function, and pathological function." (PMID 36611844, 2022). "Tumors with high POSTN expression were characterized by a higher expression level of VEGF located in the cytoplasm of tumor cells and a higher MVD compared with tumors with low expression of the glycoprotein." (PMID 36077762, 2022). "In our study, the levels of periostin in the tissue margin correlated positively with the margin and tumor levels of IL-17." (PMID 35056404, 2022). "In contrast, abnormal up-regulation of periostin expression has been observed in multiple pathological processes of various diseases, such as inflammatory diseases, fibrosis and tumor progression." (PMID 36224629, 2022). "POSTN-activated signaling pathways promote cellular survival, motility, and adhesion, which are crucial in tumor growth, angiogenesis, invasion, and metastasis." (PMID 35163164, 2022). "We further measured the protein expression levels of POSTN in the stromal and tumor regions using an independent sample set consisting of 71 archived formalin‐fixed paraffin‐embedded (FFPE) CSCC samples." (PMID 35986392, 2022). "Periostin has been reported as an interesting target for attenuating the tumor-supportive TAMs by interrupting integrin αvβ3 signaling." (PMID 35600367, 2022). "Then, we will summarize the pathologic roles of periostin in tumorigenesis and metastasis, as well as recent insights into the functions of periostin in tumor microenvironments." (PMID 36224629, 2022). "POSTN interacts with integrins expressed on the surface of tumour cells and initiates numerous signalling pathways that regulate cell proliferation, cell survival, or cell migration." (PMID 35260891, 2022). "Despite the need for immunohistochemistry, stromal periostin expression has been suggested to have a greater prognostic impact than other histological factors, including tumor budding and TAICs." (PMID 35850759, 2022). "According to recent studies, periostin expression is significantly higher in cardiac disease and tumor tissues in the majority of cancers compared to normal tissues." (PMID 36224629, 2022). "Periostin is an active molecule in tumor microenvironments promoting cancer progression through various mechanism including proliferation, invasion and angiogenesis." (PMID 35707463, 2022). "Differently, in a large cohort of PCa patients, Tishchler and colleagues reported that epithelial periostin expression significantly correlates with tumor grade and disease stage but that stromal periostin correlates only with the disease stage." (PMID 35887333, 2022).
tumor (continued). "Accordingly, the in vivo injection of recombinant POSTN together with VEGF-C boosted the lymphangiogenic response, while the metastatic potential of tumor cells was drastically reduced using a POSTN blocking antibody." (PMID 35567669, 2022). "The tumor concentrations of periostin were correlated with tumor levels of VEGF-A, IFN-γ, IL-1β and TNFα." (PMID 35056404, 2022). "POSTN is also expressed in the cancer stroma of DFSP almost exclusively in the proximity of tumor nodules and restricted to the mesenchymal side, where CD163+ TAMs and MMP-producing cells are abundant." (PMID 35409404, 2022). "Periostin acted as a niche component that promoted tumor stem cell maintenance and metastatic colonization by augmenting Wnt signaling." (PMID 35719975, 2022). "Although the overall positive rate of POSTN expression (weak, moderate, and strong) in the stroma was much higher than that in the tumor regions, only 21.1% (15/71) of the samples showed moderate/strong staining of POSTN in the stroma around the tumor." (PMID 35986392, 2022). "To study the possible role of the secreted factors in tumor promotion, we used ELISA for the detection of periostin (POSTN), fibronectin (FN) and connective tissue growth factor (CTGF)." (PMID 35406672, 2022). "We tested three potential tumor-promoting drivers in the serum derived from PE-infused mice and identified periostin, fibronectin and CTGF proteins to have elevated levels in the serum." (PMID 35406672, 2022). "POSTN secretion was elevated in FRC stimulated by tumor cell conditioned medium (B16F10 and CaSki) and VEGF-C, when compared to the control FRC." (PMID 35567669, 2022). "Cellular survival, motility, and adhesion are facilitated by POSTN-activated signalling pathways, which are essential for tumour growth, angiogenesis, invasion, and metastasis." (PMID 36555218, 2022). "Current evidence demonstrates that periostin actively contributes to tissue injury, inflammation, fibrosis and tumor progression." (PMID 36010292, 2022). "Patients with high POSTN gene expression levels experienced shorter overall survival, even after stratifying for the stromal fraction in the tumor samples (Cox proportional hazards model, p=0.001)." (PMID 34976204, 2022). "Breast tumor cell periostin expression was reported to be a powerful prognostic indicator and to correlate with tumor size, lymph node status, and human epidermal growth factor receptor 2 (HER2) status." (PMID 36224629, 2022). "We observed that POSTN mRNA relative level was increased in tumor samples when compared with a normal pancreas (p < 0.05)." (PMID 35883700, 2022). "A study of tumor material from 1007 RCC patients concluded that elevated amounts of periostin in tumor cells were correlated with sarcomatoid differentiation and more aggressive tumor cell behavior." (PMID 36077607, 2022). "The main aim of this review is to explain the current knowledge about the role of periostin in tumor development and metastasis." (PMID 36224629, 2022). "Firstly, studies suggest that periostin can facilitate the interactions between cancer cells and the tumor niche by connections with integrins to promote cell migration." (PMID 35056404, 2022). "Using Western blotting, they revealed that the expression of periostin in cancer stem cells (CD133+) was higher than in CD133− tumor cells." (PMID 36224629, 2022). "DDR2-depleted CAFs co-cultured with ES2 tumor cells had further reduction in POSTN levels compared to DDR2-expressing CAFs co-cultured with ES2 cells." (PMID 35884543, 2022). "Tumors with high stromal periostin expression showed more frequent high budding and high TAICs than those with low expression (tumor budding, 67% vs. 6%, p < 0.001; TAICs, 53% vs. 30%, p = 0.010)." (PMID 35850759, 2022). "Since collagen 1 is a ligand of DDR2, we also studied the effect of DDR2′s modulation of POSTN on tumor cell migration through a 3D collagen extracellular matrix (ECM)." (PMID 35884543, 2022).